FGFR1 (fibroblast growth factor receptor 1)
Diseases named in the same sentence as FGFR1 in open-access papers (continued):
Sharing a sentence is not in itself a finding about the gene and the disease.
craniosynostosis (34 papers, 2006 to 2026). Craniosynostosis is defined as the premature fusion of one or more cranial sutures leading to secondary distortion of skull shape resulting in skull deformities with a variable presentation. "Next to the GoF mutations, the additionally identified LoF mutations are of particular interest for disease syndromes that lead to craniosynostosis conditions, such as FGFR1-associated Pfeiffer’s, Hartsfield’s and Kallmann’s syndromes." (PMID 41361008, 2026). "In this study, we describe the main clinical characteristics of 36 patients with craniosynostosis, as well as some of the pathogenic variants of FGFR1, FGFR2, FGFR3, and TWIST1 genes." (PMID 32510873, 2020). "The suggested genetic causes of craniosynostosis are pathogenic variants in FGFR1, FGFR2, FGFR3, and TWIST1 genes." (PMID 32510873, 2020). "Using traditional anthropometry, two prior candidate gene studies reported associations between cranial vault shape and common polymorphisms in the FGFR1 gene, chosen because mutations in this gene have been implicated in craniosynostosis syndromes." (PMID 29698431, 2018). "Mutations in FGFR1 genes affect skull development, specifically suture and synchondrosis, resulting in craniosynostosis and facial abnormalities." (PMID 28129408, 2017). "A prescreen for mutations in the craniosynostosis genes FGFR1, FGFR2, FGFR3, and TWIST was performed and mutations identified in approximately 50% of cases (B. Wollnik, pers." (PMID 24498618, 2013). "In those craniosynostosis syndromes caused by FGFR1-3 mutations, alteration of signaling in the FGF/FGFR system leads to dysmorphology of the skull, brain and limbs, among other organs." (PMID 22053191, 2011). "The most common and well-characterized cases of craniosynostosis have been caused by mutation in the FGFR1 (fibroblast growth factor receptor 1), FGFR2, FGFR3, TWIST and MSX2 (muscle segment homebox 2) genes." (PMID 20108486, 2009). "In cranio-maxillofacial development, FGFR1 may cause many craniofacial abnormalities, like craniosynostosis, abnormal development of the ear and eye, tooth agenesis and cleft palate." (PMID 37833774, 2023). "Thus, the goal of this study was to describe the major clinical features associated with craniosynostosis, as well as to identify the frequency of pathogenic variants in FGFR1, FGFR2, FGFR3, and TWIST1 in a sample of Mexican patients." (PMID 32510873, 2020). "More roles have been ascribed for FGF signaling in craniofacial development, with FGFR1 specifically linked to skeletal dysplasias and craniosynostosis in both humans and mice, suggesting a mechanism by which Mir133b may regulate craniofacial development." (PMID 27471470, 2016). "Thus, loss of function mutations in FGFR1 which is involved in the development of the face, lead to the abnormal morphogenesis of the olfactory bulb, while specific gain-of function mutations in FGFR1 cause craniosynostosis." (PMID 25071724, 2014). "Skeletal phenotyping of this Fgfr1+/N330I model demonstrated markedly reduced body weight and naso-anal length, shortened long bones, and craniosynostosis, all hallmarks of the human disease." (PMID 41473314, 2025). "Conversely, gain and loss-of-function anomalies are considered responsible, respectively, for other allelic disorders, and specifically the FGFR1-related craniosynostosis/skeletal dysplasia and KAL2." (PMID 41562894, 2025). "Gain-of-function mutations in fibroblast growth factor receptor 1 (FGFR1), FGFR2 and FGFR3 are responsible for many craniosynostosis syndromes, including bent bone dysplasia and Crouzon, Apert, Pfieffer, Beare–Stevenson and Muenke syndromes, among others." (PMID 35451466, 2022). "This is clearly shown by the variants of NSD1 in cases 1 and 2, who were later assigned as affected by Sotos syndrome, and the variants identified in ERF, FGFR1, and FGFR3, all genes associated with craniosynostosis and, rather frequently, Chiari malformation." (PMID 33337535, 2021).
craniosynostosis (continued). "In previous genetic studies of normal-range cranial vault morphology, both Coussens and Van daal and Gómez-Valdés and colleagues focused on SNPs in FGFR1, a gene known to play a role in the etiology of craniosynostosis." (PMID 29698431, 2018). "The most commonly mutated genes in syndromic craniosynostosis include FGFR2, FGFR3, and FGFR1, comprising the FGFR family." (PMID 29093661, 2017). "It was found that the mutations in FGF receptors FGFR1, FGFR2, and FGFR3 in humans are associated with craniosynostosis, a characteristic phenotype of the Saethre-Chotzen Syndrome caused by dominant loss-of-function TWIST1 mutations." (PMID 24971743, 2014). "Mutations in the genes encoding fibroblast growth factor receptors 1, 2 and 3 (FGFR-1, FGFR-2, FGFR-3), TWIST and MSX2 (muscle segment homebox 2) have been identified in certain syndromic craniosynostosis." (PMID 20108486, 2009). "Targeted PCR and Sanger sequencing of FGFR1, FGFR2, FGFR3, TWIST1, and TCF12 genes resulted in the highest diagnostic rate in our cohort of craniosynostosis patients strongly recommend analysing those genes first (isolated CS and syndromic CS without intellectual disability)." (PMID 35591945, 2022). "FGFRs (FGFR1-3), TWIST, and MSX2 gene mutations are the major causes of syndromic craniosynostosis." (PMID 33731768, 2021). "DNA analysis for a specific craniosynostosis syndrome was performed, and no pathogenic variants were found in the FGFR1 (OMIM #136350), FGFR2 (OMIM #176943), FGFR3 (OMIM #134934), and TWIST (OMIM #601622) genes." (PMID 34733861, 2021). "FGFR1 specific GoF mutations are associated with craniosynostosis in Pfeiffer and Jackson–Weiss syndromes, not present neither in the proband nor in the father." (PMID 33337535, 2021). "Since Runx2 directly regulated the expression of Fgfr1–3, a positive feedback loop between FGFR signaling and RUNX2 may play an important role in the pathogenesis of craniosynostosis and limb defects caused by gain-of-function mutations in FGFR1–3." (PMID 30202094, 2018). "Apert syndrome (OMIM 101200) is characterized by premature closing of the sutures between the bones of the skull (craniosynostosis) due to gain of function mutations in the receptor tyrosine kinase fibroblast growth factor receptor 2 gene (FGFR2), one of four such receptors (FGFR1-4)." (PMID 22359510, 2012). "Interestingly, mutations in the same FGFR (either FGFR1, FGFR2 or FGFR3) can result in different craniosynostosis syndromes, thus implicating a common pathologic mechanism with FGFR gain of function in Pfeiffer, Apert, Muenke, and Beare-Stevenson syndromes." (PMID 16740155, 2006). "Lastly, in order to determine whether aberrant regulation of genes known to be involved in the aetiology of craniosynostosis underpinned any of the defects we observed, we examined the expression of Noggin, FGFR1/pFGFR1, FGFR2, Runx2 and Twist1 by immunohistochemistry." (PMID 27756203, 2016). "Overall, craniosynostosis affected 2 out of 42 patients in our cohort (5%), who both underwent direct sequencing of FGFR2, FGFR3, FGFR1 and TWIST1, with normal results." (PMID 29093661, 2017). "A murine model introduced with a dominant-negative FGFR1 construct in utero prevented suture fusion within the skull, providing proof-of-principle that the abnormal suture fusion of FGFR-related craniosynostosis may be modulated by engineered FGFR receptors." (PMID 26635999, 2015).
lung adenocarcinoma (33 papers, 2011 to 2025). A carcinoma that arises from the lung and is characterized by the presence of malignant glandular epithelial cells. "The FGFR1/JNK/Vimentin/Snail signalling cascade emerges as a pivotal pathway governing EMT in lung adenocarcinoma through TMEM176B overexpression, and this suggests that TMEM176B is a potential therapeutic target for lung adenocarcinoma." (PMID 39001509, 2024). "FGFR1 functions as a tumor promoter in various cancers including LC, non-small cell LC, and lung adenocarcinoma." (PMID 38245787, 2024). "In KRAS‐mutated lung adenocarcinoma, the use of the MEK inhibitor trametinib leads to abnormal activation of FGFR1, which leads to the development of drug resistance." (PMID 37750089, 2023). "For example, lung adenocarcinoma COLO-699 cells characterized by relatively high FGFR1 levels are largely unable to internalize T-Fc-vcMMAE and are therefore resistant to the treatment with T-Fc-vcMMAE." (PMID 33962559, 2021). "To confirm the clinical relevance of this finding, we extracted 740 lung adenocarcinoma from TCGA database, among which 54 patients were confirmed with EGFR activating mutation (n = 25), FGFR1/2 amplification (n = 15), MET amplification (n = 12), or RET fusion (n = 2)." (PMID 31221965, 2019). "IHC was performed to identify FGFR1 expression in lung adenocarcinoma." (PMID 31801598, 2019). "Mutations that could be genuine but would require further investigation in a larger patient cohort are AKT1, FGFR1 and ERBB2, each occurring in 1/8 of the clinical samples and are reported as low frequency occurring mutations in lung adenocarcinoma by the COSMIC database." (PMID 23922754, 2013). "It was reported that the FGFR1 amplification could be detected in about 10%–20% of the lung SQCC, with lower frequency in 1%–5% of lung adenocarcinoma, which was consistent with the results of our meta-analysis." (PMID 26788508, 2015). "Additionally, the frequency of FGFR1 amplification was significantly higher in males (median 17.2%, 6.6%–39.4%) than females (median 10.0%, 0.0%–15.8%) and much higher in SQCC (median 18.0%, 5.1%–28.3%) than lung adenocarcinoma (median 4.1%, 1.7%–11.5%)." (PMID 26788508, 2015). "FGFR1 true gene amplification occurred in 17.4% of SCC but was also observed in 3/26 (11.5%) tumors with neuroendocrine differentiation and 2/28 (7.1%) never-smokers with lung adenocarcinoma, including a female with a concurrent EGFR L858R mutation." (PMID 24736592, 2014). "Interestingly, among seven SNF5-deficient non-MRT lines, two of them, the rhabdomyosarcoma line KYM1 and the lung adenocarcinoma line HLC1, also displayed high levels of FGFR1 and FGFR2 transcripts, respectively, which were abrogated upon reconstitution of SNF5." (PMID 24204904, 2013). "Moreover, an intriguing observation was the coexistence of FGFR1 true gene amplification and EGFR L858R mutation in a female, never smoker patient with lung adenocarcinoma, suggesting that some NSCLCs could be co-dependent on FGFR1 and EGFR for survival." (PMID 24736592, 2014). "Lung adenocarcinoma subtypes 1–2 had the highest number of focal amplifications containing potential oncogenes (ERBB2, FGFR1, KRAS, MET), whereas LUAD-3 contained none." (PMID 33888829, 2021).
myeloproliferative disorder (33 papers, 2008 to 2025). A clonal hematopoietic stem cell disorder, characterized by proliferation in the bone marrow of one or more of the myeloid (i.e., granulocytic, erythroid, megakaryocytic, and mast cell) lineages. "The type I fusion involving FGFR1 and the FGFR1 oncogene partner (FOP) is associated with a stem cell myeloproliferative disorder, acute myeloid leukemia (AML)." (PMID 34207779, 2021). "This is a rare myeloproliferative neoplasm associated with translocation of Fibroblast Growth Factor Receptor 1 (FGFR1) on chromosome 8p11 to one of at least 14 partner genes, resulting in constitutive tyrosine kinase activity." (PMID 29110249, 2018). "Translocation of the ZNF198 and Fibroblast Growth Factor Receptor 1 (FGFR1) genes has been linked to atypical myeloproliferative disease." (PMID 25133527, 2014). "For example, chromosomal aberrations (i.e. chromosome translocation) in FGFR1 are associated with stem cell myeloproliferative disorder and stem cell leukemia lymphoma syndrome (provided by RefSeq, Jul 2008)." (PMID 25057111, 2014). "A chromosomal translocation between ZMYM2 and fibroblast growth factor receptor 1 (FGFR1) causes lymphoblastic lymphoma and a myeloproliferative disorder." (PMID 22011512, 2011). "The differential diagnosis for IHES includes primary HES associated with myeloproliferative neoplasms, such as those with genetic mutations in PDGFRA, PDGFRB, FGFR1, and JAK2." (PMID 39867100, 2024). "This represents the first reported case of durable remission achieved with Futibatinib in an FGFR1-driven myeloproliferative neoplasm." (PMID 39590377, 2024). "The KG1erythroleukemia AML cell line carries a translocation of FGFR1(FGFROP2-FGFR1) that has been described in patients with8p11 myeloproliferative neoplasms." (PMID 32315352, 2020). "ZMYM2 has initially attacted attention because it is involved in chromosomal translocations generating ZMYM2/FGFR1 fusion proteins that lead to constitutive FGFR1 signaling and the development of a myeloproliferative disease eventually progressing to AML42,43." (PMID 32439918, 2020). "The fibroblast growth factor receptor 1 (FGFR1) gene on chromosome 8 is involved in translocations with at least 14 partner genes in stem cell myeloproliferative disorder and other myeloid and lymphoid cancers." (PMID 27980689, 2016). "FOP was initially identified as a fusion with the FGFR1 gene in a case of myeloproliferative neoplasm, and was subsequently shown to localize to the centrosome and be involved in centrosome functions." (PMID 23554904, 2013). "Like the other members of FGF family grouped in cluster 2, FGF5 is involved in cell survival activities, while FOP was originally discovered as a fusion partner with FGFR1 in oncoproteins that give raise to stem cell myeloproliferative disorders." (PMID 23107425, 2012). "Chromosomal rearrangements that affect FGFR1 induce an atypical myeloproliferative disorder (MPD), characterized by dual lympho and myeloproliferation and aggressive evolution." (PMID 18412956, 2008). "Due to this similarity across these FGFR1 fusions, PLCγ1 inhibition may be a beneficial therapeutic target in treating FGFR1 translocation induced myeloproliferative neoplasms." (PMID 35574218, 2022). "Similarly, FGFR1 is translocated tomultiple chromosomal loci in a rare myeloproliferative neoplasm: myeloid/lymphoidneoplasms with FGFR1 rearrangement." (PMID 32315352, 2020). "ZMYM2, which is FGFR1 (fibroblast growth factor receptor 1) is one of the most common chaperones, and patients with ZMYM2-FGFR1 fusions frequently present with myeloproliferative neoplasms and T-lymphocytic lymphomas." (PMID 36712973, 2022). "Genetic testing excluded acute myeloid leukemia, myeloproliferative neoplasms, myelodysplastic syndromes, systemic mastocytosis, and myeloid/lymphoid neoplasms with eosinophilia, as results for PDGFRA, PDGFRB, FGFR1, or PCM1-JAK2 rearrangements were negative." (PMID 39867100, 2024).
myeloproliferative disorder (continued). "On fluorescent in-situ hybridization (FISH), myeloproliferative neoplasms (MPN) testing was negative for platelet-derived growth factor receptor-alpha (PDGFRA), platelet-derived growth factor receptor-beta (PDGFRB), and fibroblast growth factor receptor-1 (FGFR1) rearrangement." (PMID 32656011, 2020).
Pfeiffer syndrome (33 papers, 2003 to 2025). Pfeiffer syndrome (PS) is a common form of acrocephalosyndactyly, a group of inherited congenital malformation disorders, characterized by variable degrees of bicoronal craniosynostosis, variable hand and foot malformations and various other associated manifestations. "Human craniosynostoses, characterized by premature fusion of the cranial sutures in early childhood, are also caused by mutations in FGFR1, including Pfeiffer syndrome and osteoglophonic dysplasia." (PMID 39759879, 2025). "FGFR1 P250R mutation in mice, which is orthologous to the Pfeiffer syndrome mutation (FGFR1 P252R) in humans, leads to the premature fusion of calvarial sutures including frontal, sagittal, and coronal sutures." (PMID 37325554, 2023). "Mice carrying the P250R gain-of-function mutation in Fgfr1 exhibit bicoronal synostosis, thus recapitulating the clinical features of Pfeiffer syndrome, as well as a dome-shaped skull and facial asymmetry." (PMID 35451466, 2022). "FGFR1 gain of function is primarily associated with Pfeiffer syndrome, which involves multi-suture synostosis." (PMID 35451466, 2022). "Pfeiffer syndrome (PS) is an autosomal dominant disorder with three subtypes stemming from heterozygous mutations in the fibroblast growth factors FGFR1 and FGFR2." (PMID 36212619, 2022). "The authors discovered that modified FGFR1 alleles harboring SNPs had a small midface and hypertelorism, which are hallmark craniofacial features of Pfeiffer Syndrome." (PMID 35887171, 2022). "For instance, Pfeiffer syndrome is caused by a gain-of-function missense mutation in FGFR1 or activating mutation in FGFR2." (PMID 35455561, 2022). "Jackson-Weiss and Pfeiffer syndrome have also been associated with mutation in FGFR1, like the Hartsfield syndrome and the osteoglophonic dysplasia." (PMID 33919228, 2021). "A single missense mutation in FGFR1 (P252R) can cause Pfeiffer syndrome and phenocopies several Pfeiffer syndrome mutations in FGFR2." (PMID 28129408, 2017). "These facial features were similar to but were milder than those of patients with Pfeiffer syndrome, which is caused by a dysfunctional mutation in FGFR1." (PMID 28129408, 2017). "Pfeiffer syndrome is caused by a mutation in FGFR1 Ig-like domain II-III linker region (FGFR1P252R)." (PMID 28129408, 2017). "These facial features were similar to but were milder than those of individuals with Pfeiffer syndrome, which is caused by a dysfunctional mutation in FGFR1." (PMID 28129408, 2017). "These facial features were similar to those of patients with Pfeiffer syndrome, which is caused by a dysfunctional mutation in FGFR1." (PMID 28129408, 2017). "Mice carrying the P250R mutation in Fgfr1 associated with Pfeiffer syndrome were also previously shown to exhibit enhanced osteoblastic differentiation of cells within the sagittal suture." (PMID 23762837, 2013). "Mutations in Fgfr2 cause Apert, Crouzon, Jackson-Weiss, and Pfeiffer craniosynostosis syndromes, while mutations in Fgfr1 cause Pfeiffer syndrome and mutations in Fgfr3 cause Muenke craniosynostosis syndrome and Crouzon syndrome with acanthosis nigricans." (PMID 23762837, 2013). "It has also been shown that the same clinical phenotype can result from mutations in different genes, such as cases of Pfeiffer syndrome with mutations in FGFR1 and FGFR2 suggesting functional redundancy among different FGFR molecules." (PMID 20108486, 2009). "For example, FGFR1-activating mutations cause Pfeiffer syndrome." (PMID 35887171, 2022). "FGFR1 has been shown to be associated with Pfeiffer syndrome." (PMID 32722328, 2020). "A mild form of Pfeiffer syndrome can rarely be caused by a specific mutation in FGFR1." (PMID 23532954, 2013). "Similarly, metabolic studies in other FGFR1-related human diseases, such as Pfeiffer syndrome, a disease caused by FGFR1 gain-of-function variants, may also provide valuable information." (PMID 38957656, 2024).
Pfeiffer syndrome (continued). "Pfeiffer syndrome in humans, which shows similar craniofacial anomalies to those seen in Apert syndrome along with big toes and broad radially deviated thumbs, is due to a mutation in either FGFR1 (Pro252Arg) or FGFR2 (Trp290Cys, Try340Cys, Cys342Arg, or Ser351Cys, etc.)." (PMID 37325554, 2023). "For example, a KD of 2.4 × 10−8 M has been reported for the FGF2/FGFR1 complex from a patient with Pfeiffer syndrome." (PMID 33019532, 2020). "The majority of the patients with Pfeiffer syndrome present mutations in FGFR2, although a small number have also been identified in FGFR1 (<5%)." (PMID 20108486, 2009). "Premature fusion of cranial sutures is most often associated with Apert syndrome (FGFR2), Muenke syndrome (FGFR3), Crouzon syndrome (FGFR2), Pfeiffer syndrome (FGFR2, FGFR1), and Saethre-Chotzen syndrome (TWIST1)." (PMID 37629737, 2023).